MIR1283-2 (microRNA 1283-2)
Synonyms: hsa-mir-1283-2; MIRN1283-2; mir-1283-2
Gene: MicroRNA gene on chromosome 19 (53,758,232 to 53,758,318, forward strand). Ensembl gene ENSG00000221548.
Gene Ontology:
Biological process: miRNA-mediated post-transcriptional gene silencing